STAT3 (signal transducer and activator of transcription 3)
Diseases named in the same sentence as STAT3 in open-access papers (continued):
Sharing a sentence is not in itself a finding about the gene and the disease.
cardiac hypertrophy (continued). "The graphical summary depicts the established signaling and metabolic pathways that were significantly altered, most notably upregulation of cardiac hypertrophy and the STAT3 pathway as well as downregulation of synaptogenesis signaling and synaptic long-term depression." (PMID 39508990, 2025). "JAK1 is particularly important for STAT3-dependent cytokine production and macrophage recruitment by cardiomyocytes and STAT3 promotes cardiac hypertrophy and remodeling in response to pressure overload or angiotensin-II but is protective during ischemic injury." (PMID 40744288, 2025). "STAT3 is activated under a broad range of pathological conditions that lead to cardiac hypertrophy." (PMID 40028160, 2025). "Therapeutic strategies targeting STAT3 to treat cardiac hypertrophy have recently emerged." (PMID 40561034, 2025). "YOD1 promotes pathological cardiac hypertrophy by deubiquitinating and stabilizing STAT3 protein." (PMID 40561034, 2025). "Numerous studies have confirmed the crucial role of STAT3 in pathological cardiac hypertrophy." (PMID 40561034, 2025). "Transgenic overexpression of STAT3 in cardiomyocytes results in cardiac hypertrophy but confers protection from cardiomyopathy in response to doxorubicin whereas loss of STAT3 causes dilated cardiomyopathy in aged mice and exacerbates doxorubicin-induced cardiotoxicity." (PMID 40744288, 2025). "This study implied that CTS might directly inhibit STAT3 phosphorylation for attenuating cardiac hypertrophy." (PMID 36743695, 2023). "The inhibiting CaMKII and STAT3 phosphorylation lead to attenuation in cardiac hypertrophy." (PMID 37047522, 2023). "OSMR deficiency aggravated pressure overload-induced cardiac hypertrophy by modulating macrophages and OSM/LIFR/STAT3 signalling, which provided evidence that OSMR might be an attractive target for treating pathological cardiac hypertrophy and heart failure." (PMID 37120549, 2023). "Muscone could attenuate Ang II-induced cardiac hypertrophy, in part, by inhibiting the STAT3, MAPK, and TGF-β/SMAD signaling pathways." (PMID 38158445, 2023). "The determination of protein expressio for IL6 in cell supernatant by ELISA was also increased in the model of cardiac hypertrophy, and was significantly inhibited by hirudin treatment, while the phosphorylation of STAT3 and MAPK1 was also significantly inhibited." (PMID 35784743, 2022). "Therefore, STAT3 is regarded as a novel therapeutic target for delaying and reducing the progression from cardiac hypertrophy to chronic heart failure." (PMID 35365949, 2022). "Furthermore, the inhibitory effect of rhein on myocardial hypertrophy was similar to that of specific inhibitors of STAT3 and ERK signaling." (PMID 36091816, 2022). "In addition, although the selective STAT3 inhibitor, S3I‐201, was effective in reducing STAT3 phosphorylation and anti‐myocardial hypertrophy at the cellular level, it displayed a weak ability to inhibit myocardial hypertrophy in animal experiments." (PMID 35365949, 2022). "Therefore, inhibiting the activation of STAT3 is considered a potentially effective strategy for alleviating cardiac hypertrophy." (PMID 35365949, 2022). "Therefore, we suggest that rhein inhibits AngII-induced cardiac hypertrophy by targeting both the STAT3 and the P38/MAPK signaling pathways." (PMID 36091816, 2022). "Intriguingly, five pathways, such as the STAT3 pathway, were categorized into organismal growth and development (blue bars) and six pathways, including cardiac hypertrophy signaling, were involved in cellular growth, proliferation, and development (green bars)." (PMID 35241735, 2022). "Importantly, HHP-EXO significantly inhibited cardiac hypertrophy related genes, and suppressed the tissue levels of GP-130, p-STAT3, p-ERK1/2 and p-AKT." (PMID 36195937, 2022). "MiR-625-5p and miR-17-5p could bind the 3'-UTR of STAT3 mRNA and downregulated its expression to attenuate cardiac hypertrophy." (PMID 36148063, 2022).
cardiac hypertrophy (continued). "Overall, these experimental studies suggest that a modulation of STAT3 plays a central role in the development of hypertrophy and may represent a new therapeutic strategy to treat cardiac hypertrophy." (PMID 34642818, 2021). "Furthermore, Ang II employs the JAK2/STAT3 and NF-κB signaling pathways in mediating inflammatory response and cardiac hypertrophy." (PMID 34194329, 2021). "In addition, IL-6 activates the JAK2/STAT3 signaling pathway in cardiac hypertrophy, and it is produced by macrophages and cardiomyocytes in response to hypertrophic stimulus." (PMID 34194329, 2021). "In recent years, a number of studies have found that STAT3 and its related signaling pathways play a key regulatory role in the pathophysiological processes of cardiovascular system, such as myocardial hypertrophy, ischemia–reperfusion injury, and myocardial fibrosis." (PMID 34497835, 2021). "Excess ROS is also implicated in linking hyper-activity of CaMKII and STAT3 to pathological cardiac hypertrophy, but Sod1KO hearts exhibited no such evidence." (PMID 33670798, 2021). "Of further interest, signal transducer and activator of transcription 3 (STAT3) may be important for interleukin 6-mediated cardiac hypertrophy, which we showed both to be downregulated by baicalein and BHCl." (PMID 33668293, 2021). "Moreover, overexpression of STAT3 in murine cardiomyocytes leads to cardiac hypertrophy by increasing expression of hypertrophic genes, such as atrial natriuretic factor (ANF)." (PMID 34642818, 2021). "Indeed, cardiac hypertrophy due to increased fibroblast proliferation downstream of increased TWEAKR activity is supported by JAK2/STAT3 mediated hypertrophy in atrial myocytes." (PMID 33042024, 2020). "Besides, cardiac hypertrophy was enhanced by STAT3 ablation after MI in mouse hearts and consequently, capillary density was perhaps reduced in the border zone." (PMID 31709266, 2019). "Once displaced, STAT3 translocated to the nucleus and was implicated in the induction of genes for fibrosis and loss of cardiac function, but not cardiac hypertrophy." (PMID 31069236, 2019). "Our data collectively demonstrated that HSF1 is critically involved in the pathological cardiac hypertrophy after MI via modulating JAK2/STAT3 signalling and may constitute a potential therapeutic target for MI patients." (PMID 29992755, 2018). "In this study, using LAD ligation in HSF1 KO and TG mice, together with hypoxic treatment in NRCMs infected with adenovirus of HSF1 SiRNA, we uncovered that deficiency of HSF1 deteriorated cardiac hypertrophy and cardiac dysfunction after MI through enhancing the activity of JAK2/STAT3 signalling." (PMID 29992755, 2018). "The confusing role of STAT3 in the regulation of cardiac hypertrophy might be blamed to the different types of animal model or in vitro cells." (PMID 29992755, 2018). "Until recently, the role of STAT3 in hypertension-induced cardiac hypertrophy was unsettled." (PMID 30619368, 2018). "This study also reported that 60 min daily of swimming or running for 11 weeks could attenuate cardiac hypertrophy through the cardiotrophin-1-LIFR-gp130-JAK/STAT3 pathway." (PMID 30424579, 2018). "Finally, administration of anti-IL-6 antibody abolished an increase in tyrosine phosphorylation of STAT3, a major signaling molecule downstream of IL-6, in the transgenic mouse heart and prevented development of cardiac hypertrophy in transgenic mice." (PMID 28771545, 2017). "Finally, we tested the effects of administration of a specific IL-6 neutralizing antibody on cardiac hypertrophy and STAT3 phosphorylation in TG mice." (PMID 28771545, 2017). "Enhanced autophagy through STAT3 inhibition may therefore prove to be an important therapeutic modality in patients with cardiac hypertrophy." (PMID 28686615, 2017). "Loss of cardiomyocyte STAT3 did not have an effect on the development of cardiac hypertrophy with ANG II." (PMID 27899891, 2016).
cardiac hypertrophy (continued). "EP4 may mediate the cardiac hypertrophy through EGFR/ERK1/2/Stat3 signaling, whereas PGE2-EP4 signaling may protect the heart from MI/R injury through cAMP/PKA or Stat3 pathway." (PMID 27190998, 2016). "In addition, serum IL-10 overexpression can attenuate ventricular hypertrophy via the STAT3 pathway." (PMID 27936072, 2016). "The question of whether STAT3 is important for heterochromatin stability in cardiac myocytes will need to be addressed, especially under stress conditions such as cardiac hypertrophy or heart failure." (PMID 26664907, 2015). "Western blot results showed that phosphorylation levels of STAT3 and c-Myc were significantly increased in myocardium of rats with AAC and in PE-treated NRVCs compared with their controls, respectively, suggesting activation of the STAT3/c-Myc pathway during cardiac hypertrophy." (PMID 25583328, 2015). "In addition, the signal transducer and activator of transcription-3 and c-Myc were activated during myocardial hypertrophy, and inhibitions of them prevented miR-16 attenuation." (PMID 25583328, 2015). "Our findings suggest that hearts from obese mice continue to respond to elevated circulating or cardiac leptin, which may mediate cardioprotection via LepR-induced STAT3 activation, whereas signals distinct from LepR-Tyr1138 promote cardiac hypertrophy." (PMID 23841921, 2013). "Therefore, our results suggest that USP20 may prevent cardiac hypertrophy through STAT3 as a substrate." (PMID 40192103, 2025). "However, Vegfb overexpression induced cardiac hypertrophy also in aged mice and cardiac snRNA sequencing suggested that STAT3 might be involved in the VEGFB-mediated cardiomyocyte hypertrophy." (PMID 40116846, 2025). "Furthermore, CHACR inhibited the Jak2/Stat3 pathway by regulating CPT1b expression, which may be involved in the pathogenesis of cardiac hypertrophy." (PMID 40093901, 2025). "On the other hand, STAT3 is also recognized as a protective molecule, and its activation may confer cardioprotection against several cardiovascular diseases including ischemia and ischemia-reperfusion injury and cardiac hypertrophy." (PMID 38495094, 2024). "Besides, Ang II activates STAT3, which interacts with TLR4 and increases IL-6, and, in turn, promotes the second STAT3 activation, leading to an upregulated expression of genes for cardiac hypertrophy through the IL-6/glycoprotein 130 (gp130)/Janus-family tyrosine kinases 2 (JAK2) pathway." (PMID 37113698, 2023). "STAT3 could be significantly activated by interleukin- (IL-) 6 and Ca (2+)/calmodulin-dependent protein kinase II- (CaMKII-) mediated phosphorylation resulting in exaggerated pressure overload-induced mouse cardiac hypertrophy." (PMID 36743695, 2023). "A previous study showed that angiotensin II promotes cardiac hypertrophy by upregulating the expression and activity of proteasome subunits, resulting in the degradation of angiotensin II type 1 receptor (AT1R)-associated protein, and thus potentiating AT1R-mediated p38 MAPK and STAT3 signaling." (PMID 37332591, 2023). "Therefore, we speculated that PM improved cardiac hypertrophy possibly by inhibiting STAT3 activation." (PMID 35365949, 2022). "Activation of STAT3 has been suggested to reduce cardiac fibrosis or hypertrophy in DM via the inhibition of apoptosis or an increase of antioxidants, although STAT3 may promote proliferation and collagen production in isolated cardiac fibroblasts treated with a high concentration of glucose." (PMID 33503985, 2021). "Furthermore, the up-regulated type I and type III collagen, IL6, TGF-β, and down-regulated PTEN were also reversed by inhibitor BP-1-102 in miR-320 mimic, suggesting STAT3 was involved in the overexpression of miR-320-induced cardiac hypertrophy and fibrosis in vitro." (PMID 34582362, 2021).
cardiac hypertrophy (continued). "In addition, Arsb participated in the mechanism regulating cardiac hypertrophy and apoptosis by modulating the STAT3 pathway, which may be a new pathway activated by an Arsb deficiency or a new therapeutic target for MPS VI in cardiomyocytes." (PMID 31612078, 2019). "Moreover, IL-6 has also been incriminated in the pathogenesis of cardiac hypertrophy and dysfunction, through the activation of the Ca2+/calmodulin-dependent protein kinase II and STAT3 pathways." (PMID 30177883, 2018). "In addition, STAT3 in other cell types besides cardiomyocytes may be important for cardiac hypertrophy." (PMID 30619368, 2018). "There is reason to think that endogenous STAT3 may attenuate cardiac hypertrophy in certain cases." (PMID 30619368, 2018). "However, newer studies with cardiomyocyte-specific deletion of STAT3 indicate that STAT3 does not cause cardiac hypertrophy with increased blood pressure." (PMID 30619368, 2018). "Similarly, prolonged STAT3 activation during pathogenesis of cardiac hypertrophy may prove harmful for long-term preservation of cardiac function due to eventual functional deterioration of hypertrophic myocytes." (PMID 28686615, 2017). "Whether STAT3 protects the heart in other models of cardiac hypertrophy will need to be assessed." (PMID 27899891, 2016). "However, overexpression of STAT3 also results in cardiac hypertrophy." (PMID 27519769, 2016). "Therefore, we investigated whether miR-16 down-regulation in cardiac hypertrophy was also mediated through activation of the STAT3/c-Myc pathway." (PMID 25583328, 2015). "It is shown that ECSIT‐X4 interacts with STAT3, enhancing the activity of complex I, thereby promoting mitochondrial OXPHOS function during pathological cardiac hypertrophy." (PMID 39746855, 2025). "DUSP1, CCND1, STAT3, and THBS1 play important roles in the pathological process of hypertrophic cardiomyopathy (HCM), regulating myocardial hypertrophy, fibrosis, and cardiac remodelling through a complex signalling network." (PMID 40427439, 2025). "As is known, activation of Jak2/Stat3 signaling pathway would lead to the production of factors such as ANP/BNP, which are vital in cardiac hypertrophy 30,31." (PMID 40093901, 2025). "IL-6 enhances STAT3 phosphorylation in cultured CFs, whereas inhibiting STAT3 reduces IL6-induced collagen synthesis and reverses pressure overload-induced cardiac hypertrophy." (PMID 38495094, 2024). "Exosomal miRNA-148a from CDCs improves TAC-induced myocardial hypertrophy via down-regulation of GP130, leading to the inhibition of STAT3/ERK1/2/AKT signaling pathway." (PMID 39850481, 2024). "Chronic activation of JAK/STAT3 can induce cardiac hypertrophy, as evidenced by Ang II-induced activation of TLR4 and STAT3, promoting hypertrophy via the IL-6/JAK2/STAT3 pathway." (PMID 38495094, 2024). "We examined the effects of muscone on the TGF-β/SMAD, STAT3 and MAPK signaling pathways involved in Ang II-induced cardiac hypertrophy and inflammation." (PMID 38158445, 2023). "We have recently reported that STAT3 is activated in both Ang II- and TAC-induced cardiac hypertrophy and fibrosis." (PMID 37153745, 2023). "Signal transducer and activator of transcription 3 (Stat3), one of the STAT members, has increasingly gained focused attention due to its significant roles in metabolic diseases, cardiac hypertrophy, heart failure and arteriosclerosis." (PMID 37891701, 2023). "Multiple intracellular signaling pathways participate in cardiac hypertrophy, including the IGF1R/PI3K/AKT, EGFR/MAPK, GP130/Jak/STAT3 and calcineurin/NFAT pathways." (PMID 35855640, 2023). "Multiple intracellular signaling pathways participate in cardiac hypertrophy, including PI3K/AKT, EGFR/MAPK and GP130/JAK/STAT3." (PMID 35855640, 2023). "In recent years, many studies have found that STAT3 and its related signalling pathways also play a key regulatory role in the cardiovascular system, such as IHD, HF and myocardial hypertrophy." (PMID 36225565, 2022).
cardiac hypertrophy (continued). "Then, the phosphorylation of STAT3(Tyr705) and JAK2(Tyr1007/1008) were examined to elucidate the mechanism which PM alleviates cardiac hypertrophy." (PMID 35365949, 2022). "Inhibition of STAT3 activation by celastrol decreased cardiac fibrosis and hypertrophy in Ang II- and TAC-induced cardiac hypertrophy mouse models and in rat renal artery stenosis model." (PMID 36195937, 2022). "In summary, our study provides evidence that PM protects against pathological cardiac hypertrophy by inhibiting levels of the STAT3 phosphorylation and nuclear translocation to suppress the activation of JAK2/STAT3 signalling pathway." (PMID 35365949, 2022). "Our results collectively demonstrated that PM prevented cardiac hypertrophy in vivo and in vitro by inhibiting the JAK2/STAT3 pathway." (PMID 35365949, 2022). "Many experiments have shown that STAT3 and p38 MAPK are central to the development of cardiac hypertrophy." (PMID 36091816, 2022). "These cells produce various proinflammatory cytokines and ROS that activates multiple signaling pathways (CaNA/STAT3, TGF-β1/Smad2/3, IKKɑ/NF-kB, and NOX1/4), thereby leading to cardiac hypertrophy, fibrosis, inflammation and DNA damage (cardiac remodeling)." (PMID 36467095, 2022). "To investigate the mechanism of rhein on cardiac hypertrophy induced by TAC operation in mice, we examined the effects of rhein on STAT3 and P38/MAPK signaling pathways involved in proliferation and inflammation of cardiac hypertrophy cells." (PMID 36091816, 2022). "We conclude that rhein reduces TAC-induced cardiac hypertrophy via targeted inhibition of the molecular function of ERK and downregulates STAT3 and p38 MAPK signaling." (PMID 36091816, 2022). "What is more, BP-1-102, an inhibitor of STAT3, was injected into the culture medium of cardiac fibroblasts transfected with miR-320 mimic to investigate whether STAT3 signaling was involved in the overexpression of miR-320-induced development of cardiac hypertrophy and fibrosis." (PMID 34582362, 2021). "To investigate the mechanisms of loganin acting on cardiac hypertrophy, we detected effects of loganin on the JAK2/STAT3 and NF-κB signaling pathways, which are involved in cardiac hypertrophy and inflammation induced by Ang II." (PMID 34194329, 2021). "Our previous work demonstrated that RORα mitigated Ang II-induced cardiac hypertrophy through the regulation of cardiomyocyte IL6 and STAT3 signaling." (PMID 34756888, 2021). "Mechanistically, we revealed that miR-320 mimics aggravated the pressure overload and induced cardiac hypertrophy and fibrosis via the IL6/STAT3/PTEN axis." (PMID 34582362, 2021). "In NE-induced cardiac hypertrophy, the protein expression of JAK2 and STAT3 is significantly upregulated, further promoting the development of cardiomyocyte hypertrophy." (PMID 34221090, 2021). "Combining with TG-101348 and JSI-124, the specific inhibitor of JAK2, we confirmed that the inhibitory effect of magnolol on myocardial hypertrophy and fibrosis is related to the inhibition of the JAK2/STAT3 signaling pathway." (PMID 34764873, 2021). "Numerous intracellular signalling pathways participate in cardiac hypertrophy accompanied by increased protein synthesis, such as IGF1R/PI3K/AKT, EGFR/ MAPKs, gp130/Jak/STAT3 and calcineurin/NFAT." (PMID 32343488, 2020). "According to our in vitro and in vivo data, FNDC5 absence/knockdown led to an enhanced phosphorylation level of JAK2 and STAT3 under high lipid treatment (HFD/PA) accompanied by aggravated inflammation, oxidative stress and cardiac hypertrophy." (PMID 30940158, 2019). "Based on these findings, miR-154-5p promoted cardiac hypertrophy and apoptosis mainly by inhibiting Arsb expression, subsequently attenuating the activation of the p38 MAPK/JNK/STAT3 pathway." (PMID 31612078, 2019). "STAT3 is the most important effector of the JAK2 in the initiation and development of cardiac hypertrophy." (PMID 30940158, 2019).